G6PD (glucose-6-phosphate dehydrogenase)
Diseases named in the same sentence as G6PD in open-access papers (continued):
Sharing a sentence is not in itself a finding about the gene and the disease.
G6PD deficiency (continued). "The use of the qualitative fluorescent spot test rather than a quantitative test to diagnose G6PD deficiency in neonates might have underestimated its impact; the G6PD FST has been described not to perform well in neonates possibly due to the higher G6PD activity in neonates then adults." (PMID 29895274, 2018).
malaria (528 papers, 2005 to 2026). Malaria is a serious and sometimes fatal disease caused by a parasite that commonly infects a certain type of mosquito which feeds on humans. "Tafenoquine and primaquine are drugs used in the treatment of malaria due to Plasmodium vivax, but can cause hemolysis in patients with glucose-6-phosphate dehydrogenase (G6PD) enzyme deficiency." (PMID 41849481, 2026). "This mirrors our observations in erythrocytes from individuals who are deficient in the pentose-phosphate-pathway enzyme G6PD-a trait associated with protection against malaria in some settings-and highlights a common ROS-based mechanism of malaria resistance." (PMID 41708853, 2026). "In this preliminary study, Wondfo G6PD/Hb Test demonstrates promising diagnostic performance to support malaria case management." (PMID 40597115, 2025). "This genetic heterogeneity reflects the evolutionary pressure, particularly from malaria, that has shaped the regional distribution of G6PD variants in Southeast Asia." (PMID 40966243, 2025). "This risk is significant in the context of malaria elimination programs, where 8-aminoquinoline-based therapies for radical cure require prior G6PD screening to avoid severe hemolytic reactions." (PMID 41002317, 2025). "The widespread use of primaquine and tafenoquine for malaria eradication necessitates careful risk stratification, as these drugs are strong oxidants capable of inducing severe hemolysis in G6PD-deficient individuals." (PMID 40486677, 2025). "Malaria has been the selective force for G6PD deficiency (for both P. falciparum and P. vivax) and Duffy-negative phenotype (for P. vivax) to provide protection from these malaria species or, at least, from severe malaria." (PMID 41452897, 2025). "G6PD testing should be integrated into standard malaria diagnostic services or newborn screening should be implemented in high-prevalence areas." (PMID 40225210, 2025). "This evolutionary trade-off providing some resistance to malaria while increasing the risk of hemolysis under oxidative stress explains the persistence and prevalence of G6PD deficiency in malaria-endemic regions." (PMID 40689289, 2025). "The postulated mechanism is that the uncontrolled oxidative stress in G6PD deficient red cells makes them inhospitable to the malaria parasites." (PMID 39502751, 2024). "In malaria patients, one male and two females were considered G6PD deficient and two females were considered G6PD intermediate." (PMID 38308253, 2024). "The majority of these variants are found in the Hb genes and G6PD, which are believed to be the result of heterozygous advantage in regions with a high prevalence of malaria." (PMID 38167091, 2024). "TQ’s impact as a new radical cure drug agent against P. vivax malaria has been constrained in part by the risk of hemolytic toxicity in G6PD-deficient human populations that are largely coincident with the malaria belt geography." (PMID 38640243, 2024). "Studies dating back to the early 1960s postulated that G6PD deficiency inhibits the occurrence of malaria." (PMID 38179076, 2024). "Several reports indicate that G6PD deficiency confers protection against all forms of malaria, especially in hemizygous deficient males, and heterozygous deficient females, however, results have been conflicting." (PMID 39502751, 2024). "Parameters used in the economic evaluation, including diagnostic accuracy of G6PD screening; risk of haemolysis, severe malaria and death; unit costs in 2020 US$; and length of illness and weights for DALYs." (PMID 38194420, 2024). "The combination of c.1311C>T and c.1365-13T>C resulted in a wide range of G6PD activity in this study, ranging from intermediate to normal and the frequency of these combined polymorphisms was higher in malaria-positive samples." (PMID 38308253, 2024). "Despite this protective effect, malaria therapeutics are still complicated by drug-induced haemolysis in G6PD-deficient individuals." (PMID 38308253, 2024).
malaria (continued). "One of its research outputs points out a relationship between malaria and glucose 6 phosphate dehydrogenase (G6PD) deficiency, a genetic disorder that affects red blood cells." (PMID 38179076, 2024). "At the individual level, it will enable the safe treatment of more patients with deficient and intermediate G6PD activity, diminishing the risk of recurrent malaria and acute haemolytic anaemia." (PMID 39488711, 2024). "Considering the problems associated with the use of primaquine in G6PD-deficient individuals, scientists have been devising new transmission-blocking agents and repositioning non-malaria medications." (PMID 39065810, 2024). "We identify the G6PD Mediterranean mutation associated with malaria resistance in three out of four ancient Bahraini samples and estimate that it rose in frequency in Eastern Arabia from 5 to 6 kya onward, around the time agriculture appeared in the region." (PMID 38417441, 2024). "Ascending dose primaquine regimens in G6PD-deficient malaria patients exploit the same pharmacodynamic principle underling the current once weekly treatment recommendation." (PMID 38319064, 2024). "It has also been proposed that G6PD deficiency confers a relative protection against severe malaria, as reflected by the geographic frequency overlap between the two." (PMID 38308253, 2024). "The HCSP, highlighted the risk of underestimating G6PD levels if G6PD screening is performed early during an acute malaria episode (i.e., before day 14)." (PMID 38725027, 2024). "The spread of these variants is closely correlated with malaria: in areas where the disease was endemic, the G6PD Mediterranean, G6PD Cassano, G6PD Seattle, and G6PD A-pathogenic variants (PVs) are mainly observed." (PMID 39457422, 2024). "The remarkable polymorphism of G6PD has contributed to understanding how individual mutations affect enzyme function and their roles in human evolution under malaria selection." (PMID 39070600, 2024). "Primaquine (PQ) is also administered for malaria treatment but its haemolytic toxicity in people with glucose-6-phosphate dehydrogenase (G6PD) deficiency, a common genetic trait in malaria-endemic regions, limits its use." (PMID 36986890, 2023). "Nonetheless, there is limited knowledge about the effects of iron-fortified micronutrient diets on ABO blood groups, haemoglobin and G6PD genotypes and the risk of contracting malaria and anaemia among pre-school children living in malaria endemic areas." (PMID 36959634, 2023). "In our study, from a malaria-endemic area in northern Brazil, the G6PD variant African A − (G202A/A376G) was predominant among individuals with low activity." (PMID 37513742, 2023). "The information on the confirmation of G6PD deficiencies by molecular tests and their relationship with malaria management in the presence of different molecular variants is also limited." (PMID 37176619, 2023). "The G6PD deficient allele frequency within the cohort was low (0.011) with a high prevalence reported in malaria endemic regions, e.g., 33% of prevalence across Africa has been reported previously." (PMID 37284308, 2023). "The G6PD genotypes did not influence the anaemic status at the end of the MNP intervention even though G6PD-deficient RBCs are known to be more vulnerable to oxidative stress, which prevents malaria parasitization and eventually reduces anaemia." (PMID 36959634, 2023). "In the West African and Asian populations, the G6PD 968 C and the Mediterranean 563 C > T variant were associated with enzyme deficiency and protection against severe malaria." (PMID 37340364, 2023). "The most effective management strategy for malaria elimination and neonatal jaundice in G6PD-deficient neonates is early diagnosis of the hereditary condition." (PMID 37388931, 2023).
malaria (continued). "Because individuals with deficient as well as intermediate levels of G6PD activity are at risk of developing adverse effects when receiving radical treatment for malaria, the WHO recommends G6PD testing before prescribing 8-aminoquinolines." (PMID 37967096, 2023). "Primaquine for radical cure of Plasmodium vivax malaria poses a potentially life-threatening risk of haemolysis in G6PD-deficient patients." (PMID 37764985, 2023). "G6PD gene mutation is widespread and heterogeneous across the study area where primaquine would be valuable for malaria control and elimination." (PMID 38062464, 2023). "Due to the high prevalence of G6PD in sub-Saharan Africa, which results in diminished activity of the G6PD enzyme, it is believed that G6PD genetic variants on the X chromosome arose due to selection pressure exhibited by malaria on the human genome." (PMID 37495620, 2023). "The G6PD MahidolG487A mutation in malaria patients had an MAF of 7.1% in the study population (18 of 255), 7.4% in individuals from Myanmar (14 of 189), 5.7% in Thais (2 of 35) and 12.5% in Karen (2 of 16)." (PMID 36038921, 2022). "A total of 34 out of 39 participants classified as intermediate deficient when aparasitemic had normal activities when enrolled with malaria, 4 out of 6 participants diagnosed as deficient when aparasitemic were G6PD normal when tested during acute malaria." (PMID 35544453, 2022). "Our study found that the G6PD SNP +10588_A > G (rs762515) yielded a significant association with protection from severe malaria in the Senegalese population." (PMID 35811813, 2022). "Using a multivariate regression and additive model, estimates of the impact of human HBB and G6PD polymorphisms on malaria incidence were performed." (PMID 35811813, 2022). "A case-control study showed a significant association between G6PD A- and risk of severe malaria, with protection against cerebral malaria but increased risk of severe anemia." (PMID 35811813, 2022). "Although so much current research shows that G6PD deficiency protects against malaria, especially falciparum malaria, the evidence is still insufficient." (PMID 36160421, 2022). "This study lacked information on other RBC polymorphisms that have been associated with clinical outcomes of malaria, e.g. glucose-6-phosphate dehydrogenase, complement receptor-1 and haemoglobinopathies." (PMID 36050680, 2022). "The fact that reticulocytes of G6PD-deficient patients have normal G6PD activity means that reticulocyte levels should be accounted for in studies investigating the link between G6PD deficiency and malaria." (PMID 36386653, 2022). "For example, in cases of acute hemolysis associated with malaria, the erythrocyte population is enriched for young erythrocytes and reticulocytes, which have near-normal G6PD enzyme levels." (PMID 35008062, 2022). "Frequencies and single nucleotide polymorphism (SNP) of G6PD gene and association analysis with susceptibility to severe malaria (SM)." (PMID 35811813, 2022). "For example, it would be beneficial to perform joint pharmacogenetic typing of G6PD along with CYP2D6 when considering Vivax malaria control with primaquine, as G6PD deficiency can result in primaquine-induced hemolysis." (PMID 35217695, 2022). "Our data report HBB and G6PD polymorphisms in the Senegalese population and their correlation with severe/mild malaria and outcome." (PMID 35811813, 2022). "Glucose-6-phosphate dehydrogenase (G6PD) deficiency offers some protection against malaria; however, the degree of protection is poorly described and likely to vary with G6PD genotype and Plasmodium species." (PMID 35193663, 2022). "The present study aimed to elucidate such an association by thoroughly investigating the haematological indices in malaria patients with G6PD and PKLRR41Q variants." (PMID 36038921, 2022). "The main aim of the present study was to examine the haematological profiles in malaria patients with G6PD or PKLR mutations." (PMID 36038921, 2022).
malaria (continued). "The SNPs HbS (rs334), HbC (rs33930165) and G6PD +10588A > G (rs762515) were associated with protection against severe malaria in the three regions by comparison of SM vs UM with higher frequency in UM group." (PMID 35811813, 2022). "For G6PD, the SNP +10588 A > G (rs762515) yielded a significant association with protection from severe malaria in Senegalese populations." (PMID 35811813, 2022). "Similar study in Upper Myanmar showed that among 50 malaria patients with G6PD variants, 25 (50.0%), 17 (34.0%), and 8 (16.0%) were infected with P. falciparum, P. vivax, and co-infections with both P. falciparum and P. vivax, respectively." (PMID 36076204, 2022). "Blood samples from 255 malaria patients from Thailand, Myanmar, Laos, and Cambodia were collected to determine haematological profile, G6PD enzyme activity and G6PD deficiency variants." (PMID 36038921, 2022). "Several studies have revealed that the complexity of phenotypic and genotypic variation of the Duffy system and the variants of G6PD (A-) is geographically variable across human populations in areas in which malaria is endemic." (PMID 35527254, 2022). "It has been observed that most malaria patients especially G6PD-deficient patients usually experience oxidative stress and severe anemia when treated with primaquine." (PMID 36399959, 2022). "In Bonda, Chutkiya Bhunjia, Didayi, Kutia Konda and Paudi Bhuyan, all the G6PD deficient individuals were malaria positive as well." (PMID 36384674, 2022). "Complete deficiency for G6PD is embryonic-lethal in mice but hypomorphic G6PD mutations are common in certain human populations, perhaps because they protect against malaria." (PMID 35110412, 2022). "A high frequency of G6PD mutations was found in the malaria-endemic areas along the Thai–Myanmar border, and G6PD Mahidol (487 G>A) was the most common variant in this area, while G6PD Viangchan (871 G>A) was commonly found in central and southern regions." (PMID 36508454, 2022). "Although primaquine is a potent orthodox antimalarial drug, there are cases of some side effects arising from its use in the treatment of G6PD-deficient and sickle cell patients suffering from malaria; side effects such as oxidative stress and severe anemia." (PMID 36399959, 2022). "Malaria also causes haemolysis, leading to the replacement of older erythrocytes with low G6PD activity by reticulocytes and young erythrocytes with higher activity." (PMID 35544453, 2022). "Epidemiological evidence for the association between G6PD deficiency and a reduction in the risk of severe malaria has been accompanied by the results of in vitro work showing that parasite growth is slowest in G6PD-deficient cells." (PMID 36231003, 2022). "Deficiency in the G6PD gene is suggested to be protective against malaria; however, a recent screen identified polymorphisms in the G6PD gene to be associated with a significant risk of severe malaria." (PMID 35291755, 2022). "Correlations between altered G6PD activity due to mutations in malaria patients and haematological phenotypes prior to treatment with anti-malarial drugs have not been well studied." (PMID 36038921, 2022). "It is essential to perform additional screening of HBB and G6PD loci to identify potential variants associated with susceptibility to severe malaria and corresponding hematologic parameters." (PMID 35811813, 2022). "In participants from three ecological zones, we characterised polymorphisms on HBB and G6PD genes where the malaria endemicity was different." (PMID 35811813, 2022). "Another concern of Vc-mediated Plasmodium inhibition is individuals with glucose-6-phosphate dehydrogenase (G-6-PD) deficiency, an observed genetic trait in malaria-endemic regions." (PMID 34046404, 2021). "Currently, radical cure for malaria involves either primaquine or tafenoquine, both of which cause acute hemolytic anemia in patients with an inherited defect in G6PD enzymatic activity." (PMID 34270547, 2021).